LEP (leptin)
Diseases named in the same sentence as LEP in open-access papers (continued):
Sharing a sentence is not in itself a finding about the gene and the disease.
Crohn disease (11 papers, 2011 to 2024). A gastrointestinal disorder characterized by chronic inflammation involving all layers of the intestinal wall, noncaseating granulomas affecting the intestinal wall and regional lymph nodes, and transmural fibrosis. "Leptin as well as adiponectin favored the polarization of anti-inflammatory macrophages, the dominant macrophage population detectable in creeping fat of Crohn's disease patients." (PMID 30369924, 2018). "Leptin expression also increases in the colon tissues of patients with ulcerative colitis and Crohn’s disease." (PMID 28170448, 2017). "However, independent studies revealed a strong up-regulation of leptin expression in the mesenteric fat of Crohn's disease patients." (PMID 30369924, 2018). "Finally, by culturing creeping fat and MAT explants from Crohn's disease patients with conditioned medium from probiotics cultures we have provided evidence that probiotics modulate leptin release." (PMID 21829567, 2011). "Recombinant leptin exerts diverse pro-inflammatory effects on immune cell differentiation and function, including the metabolic reprogramming of immune cells and the induction of TNFα, ultimately aggravating Crohn’s disease, which can be reversed by anti-TNFα therapy." (PMID 33921758, 2021). "For instance, the creeping fat in patients with Crohn’s disease (CD) has been referred to as the inflammatory mesenteric fat hypertrophy mediated by a rise in proinflammatory adipokines, including TNF-α, TWEAK, leptin and IL-1β." (PMID 28425943, 2017). "Among these leptin, resistin, adiponectin, and SRFP5 appear to present a promising key role in the development and suppression of the inflammatory response, and their role has been confirmed in other inflammatory disorders, such as Crohn’s disease." (PMID 38338780, 2024). "In Crohn's disease patients creeping fat is infiltrated by activated macrophages and releases high amount of TNF-α and leptin, a proinflammatory adipokine, indicating that this tissue could play a mechanistic role in maintaining local and systemic inflammation." (PMID 21829567, 2011). "Interestingly we found that, while creeping fat releases higher levels of leptin, IL-6 and TNFα compared to the MAT explants obtained from Crohn's disease patients, incubation with VSL#3-CM conter-regulates the production of these inflammatory mediators and abrogates the generation of leptin." (PMID 21829567, 2011).
emphysema (11 papers, 2009 to 2024). "Incident low muscle mass is associated with lower lung function, emphysema progression, and the persistence of low circulating leptin levels at follow-up." (PMID 37737171, 2023). "Adiponectin-deficient mice have been reported to be protected from tobacco-induced emphysema, while low levels of leptin are associated with loss of respiratory muscle function and a decline in FEV1." (PMID 32218378, 2020). "A research group from Maastricht University, in the Netherlands enrolled 15 male subjects with bronchitis predominant COPD and 27 male subjects with emphysema predominant disease to study the association between systemic inflammation, leptin and energy balance in COPD." (PMID 23101436, 2012). "Dysregulated adipokine metabolism – with adiponectin, leptin, and resistin being commonly implicated adipokines – is also prevalent in COPD and is associated with inflammatory response regulation, emphysema, and skeletal muscle dysfunction." (PMID 37737171, 2023). "Over time, individuals in this subgroup demonstrated greater active smoking prevalence, more airflow obstruction, greater emphysema progression, and lower circulating leptin compared to individuals with stable muscle mass." (PMID 37737171, 2023). "Leptin and adiponectin, nodes in the percent emphysema network with strong edges connecting them to growth hormone receptor, are both proteins released from adipose tissue." (PMID 32218378, 2020). "TNF-α was also positively correlated with leptin/% FM in both chronic bronchitis and emphysema (r = 0.774, p < 0.001 and r = 0.499, p = 0.015 respectively)." (PMID 19344528, 2009). "This correlation between TNF-α and leptin was true even when we studied patients with chronic bronchitis and emphysema separately (r = 0.719, p < 0.001 and r = 0.505, p = 0.014 respectively)." (PMID 19344528, 2009). "Low levels of anabolic hormones could act synergistically with the catabolic activity of cytokines and leptin and play a role in the weight loss and decreased muscular mass usually seen in COPD patients and mainly those with emphysema." (PMID 19344528, 2009). "Plasma leptin concentrations and the leptin/adiponectin ratio exhibited a significantly inversed correlation with initial FEV1 in emphysema patients." (PMID 26593914, 2015). "A positive correlation between serum leptin and soluble TNF-α receptor levels was observed in patients with emphysema." (PMID 23101436, 2012). "Concentrations of plasma cytokines, leptin and IGF-I in patients with chronic bronchitis and emphysema on admission to the hospital (D1)." (PMID 19344528, 2009). "Concentrations of plasma cytokines, leptin and IGF-I in patients with chronic bronchitis and emphysema on D15." (PMID 19344528, 2009). "Leptin was positively related to TNF-α on D1 of the exacerbation and this correlation also applied to both subgroups of COPD patients, thus chronic bronchitis and emphysema." (PMID 19344528, 2009).
fibromyalgia (11 papers, 2014 to 2025). A chronic disorder of unknown etiology characterized by pain, stiffness, and tenderness in the muscles of neck, shoulders, back, hips, arms, and legs. "The administration of LPS to healthy individuals with moderately severe fibromyalgia augmented leptin levels and repressed fractalkine levels, as measured using a multi-cytokine ELISA." (PMID 41007675, 2025). "A small study showed that pain intensity from day-to-day varied with leptin concentration in women with fibromyalgia." (PMID 39716315, 2024). "In one study involving patients with fibromyalgia, the leptin level was significantly decreased after resistance exercise for 15 weeks in lean women, but not in overweight and obese individuals." (PMID 35346353, 2022). "A comparison of the leptin levels adjusted by fat mass showed similar results, with lower levels present in the group with fibromyalgia when compared with controls (531.63 ± 365.13 pg/mL/kg versus 684.05 ± 300.27 pg/mL/kg, respectively; p < 0.05)." (PMID 28226002, 2017). "Compared with the control group, the fibromyalgia group had lower unadjusted leptin levels (12,812.2 ± 8,619.3 pg/mL versus 18,316.3 ± 10,190.2 pg/mL, respectively; p < 0.005)." (PMID 28226002, 2017). "These authors demonstrated that leptin levels were significantly lower in patients with fibromyalgia than in controls." (PMID 28226002, 2017). "We found that leptin levels correlated positively and significantly with the BMI in the entire cohort (r = 0.47, p < 0.0001), in the fibromyalgia group (r = 0.36, p = 0.009), and in the control group (r = 0.70, p < 0.0001)." (PMID 28226002, 2017). "Leptin levels in musculoskeletal conditions and fibromyalgia have shown contradicting results." (PMID 28226002, 2017). "Reports have suggested higher leptin levels in patients with fibromyalgia compared to age, sex and BMI matched controls and that fibromyalgia patients tend to demonstrate an overexpression of leptin independent of the contribution of their overweight." (PMID 39716315, 2024). "The beneficial effect of exercise on serum leptin in patients with RA is similar to the effect observed in overweight patients with RA, unlike fibromyalgia." (PMID 35346353, 2022). "In none of the general groups (fibromyalgia patients and controls) there was a correlation between serum levels of leptin with clinical parameters related to fibromyalgia, such as FIQ scores, PHQ-9 results, pain threshold, or TPs count." (PMID 28226002, 2017). "We did not observe a correlation between leptin levels and clinical parameters of fibromyalgia among patients with this condition." (PMID 28226002, 2017). "The authors suggested that the lack of leptin or resistance to its action could favor a depressive status, and this factor could lead to worsening of fibromyalgia." (PMID 28226002, 2017). "Since leptin has a suppressive action in the HPA axis, its lower levels in patients with fibromyalgia could collaborate with a hyperactivity of the axis, but we cannot rule out that a variability in leptin levels in humans could hinder the evaluation of this adipokine." (PMID 28226002, 2017).
Genetic obesity (11 papers, 2011 to 2025). "Genetic obesity results from loss-of-function mutations, including those affecting the leptin–melanocortin system, which regulates body weight." (PMID 40001512, 2025). "As a model for genetic obesity we used leptin-deficient ob/ob mice that were compared with corresponding wt littermates." (PMID 21731698, 2011). "FADD‐D was introduced into ob/ob mice to create FADD‐D/ob/ob double‐mutant mice to determine whether the FADD‐D mutation could prevent genetic obesity as caused by leptin deficiency." (PMID 27357657, 2016). "The experiments failed as no changes were recorded between treated and untreated animals (data not shown), unsurprisingly suggesting that leptin-independent pathway(s) exist(s) in the pathophysiology of genetic obesity that does not involve the MCH pathway." (PMID 33673598, 2021).
kidney failure (11 papers, 2008 to 2024). An acute or chronic condition that is characterized by the inability of the kidneys to adequately filter the blood. "Excluding the patient with renal failure on dialysis (patient 3), the mean leptin levels were lower in the FPLD group compared with controls (p = 0.04), while adiponectin and chemerin levels were not significantly different." (PMID 38321009, 2024). "On the other hand, leptin is mainly cleared by the kidney, therefore serum concentrations are increased in patients with kidney failure and those undergoing dialysis." (PMID 38627329, 2024). "The indicators of kidney failure including urinary protein, neutrophil gelatinase-associated lipocalin (NGAL), renal type I and IV collagen deposits and leptin content, and serum creatinine were also increased by HFF." (PMID 37630806, 2023). "Previous studies reported that serum leptin levels were positively correlated with PhA, in hemodialysis patients and with serum albumin in peritoneal dialysis patients." (PMID 30089153, 2018). "Visfatin levels correlated with biomarkers of renal failure, liver dysfunction, and other adipokines (e.g., resistin, leptin, and adiponectin) in critically ill patients." (PMID 30224938, 2018). "Even the decrease of renal clearance can augment serum leptin concentration in ESRD patients; however, one-quarter of chronic peritoneal dialysis patients maintained normal serum leptin level." (PMID 29304064, 2018). "In contrast, endotoxins and inflammation in kidney failure have been shown to up regulate leptin production." (PMID 20066136, 2008). "Levels of adipocytokines, such as adiponectin and leptin, were elevated in renal failure." (PMID 33082885, 2020). "In addition, high serum leptin levels could be an novel marker to survey kidney failure in clinical practices." (PMID 36619557, 2022).
macrosomia (11 papers, 2017 to 2025). "By contrast, infants with a PI ≥ 97th percentile have asymmetric macrosomia associated with a higher fat mass, and cord blood insulin and leptin levels." (PMID 32346630, 2020). "Increased leptin levels in obese pregnant women are significantly correlated with fetal overgrowth, leading to macrosomia." (PMID 37497352, 2023). "Previously we have also shown that P HFHS dams have increased leptin and triglyceride levels as well as increased lipolysis, which can lead to increased free fatty acids which are also thought to impact fetal growth and lead to macrosomia." (PMID 36520818, 2022). "This brings up the assumption that Leptin might affect the association between UC C-peptide concentration and GWG, as well as UC C-peptide and macrosomia." (PMID 36224521, 2022). "Thus, the correlations between specific OTUs/phyla/genera and cord blood insulin, IGF-1 and leptin level may help to explain their roles in the development of fetal macrosomia." (PMID 29137266, 2017). "It showed that leptin (14.84±6.71 vs. 7.50±3.82, P = 0.008) and IGF-1 (93.20±56.88 vs. 51.99±22.19, P = 0.047) concentrations were elevated in fetal macrosomia." (PMID 29137266, 2017). "Current study also shows that LGA newborns had significantly higher cord serum C-peptide levels in addition to higher leptin and insulin levels than AGA newborns, which is consistent with previous studies revealing that C-peptide levels in macrosomia were significantly higher than in AGA infants." (PMID 31975995, 2019).
malaria (11 papers, 2011 to 2025). Malaria is a serious and sometimes fatal disease caused by a parasite that commonly infects a certain type of mosquito which feeds on humans. "Tie2, sFlt1, sENG and leptin were associated to growth parameters in newborns of mothers who had malaria during pregnancy." (PMID 41335627, 2025). "In this context, it is interesting to note that malaria parasites sequestered in peripheral white adipose tissue cause enhanced circulating levels of leptin, an adipokine that has been correlated to the morbidity of cerebral malaria." (PMID 37153157, 2023). "Low levels of leptin can lead to reduced immune response, resulting in increased risk of malaria associated with wasting." (PMID 31010435, 2019). "The aim of this study was to determine plasma levels of leptin and investigate its associations with body composition, malaria, haemolytic, sickling and inflammatory parameters." (PMID 21612659, 2011). "Conversely, malaria patients show decreased blood leptin, with leptin being suggested to be used as one of the prognostic markers of malaria." (PMID 39492784, 2024). "In this study, lower levels of Leptin were observed in women with malaria over the course of pregnancy, consistent with prior findings." (PMID 31574087, 2019). "Altered kinetics were also observed in women with malaria at Visit 1 for the following angiogenic and metabolic factors: sEng (χ2 = 38.3, p < 0.001), Angptl3 (χ2 = 13.3, p = 0.001), and Leptin (χ2 = 13.2, p = 0.001)." (PMID 31574087, 2019). "Moreover, hormones influence the immune system and thus can regulate the severity of infection, with leptin antagonists and cortisol modulators been explored to target hormonal pathways against malaria." (PMID 39492784, 2024). "Importantly, the level of leptin in serum of malaria patients has been recently reported to be used as prognostic markers of treatment outcomes and pathogenesis of malaria patients." (PMID 30534129, 2018). "Furthermore, leptin exerts central effects on hypothalamic-pituitary function and these outcomes might affect the severity of malaria disease." (PMID 30534129, 2018). "At Visit 1, compared with uninfected women, malaria-infected women had significantly higher levels of CHI3L1, CRP, sICAM-1, IL-18BP, sTNFRII, and sEng and lower levels of Leptin (p ≤ 0.005)." (PMID 31574087, 2019).
rheumatic diseases (11 papers, 2010 to 2022). "Increasing evidence suggests that leptin exerts potent modulatory actions in the network of factors implicated in the pathophysiology of rheumatic diseases such as OA and RA." (PMID 35270000, 2022). "Leptin also plays a major role in the anorexia and cachexia condition of inflammatory diseases caused by pathogens, collagen vascular disease, and even cancer." (PMID 34220807, 2021). "Leptin has been associated with rheumatic diseases due to its ability to modulate bone and cartilage metabolism." (PMID 24741591, 2014). "In addition to its well-known actions on immune system, leptin has also been associated with rheumatic diseases due to its ability to modulate bone and cartilage metabolism." (PMID 22910888, 2012). "Leptin is an immunomodulatory cytokine, which was observed to be increased in patients with rheumatic diseases." (PMID 36141644, 2022). "Although many aspects are still unclear, this review summarizes the current knowledge on the role of leptin in cartilage pathophysiology and in certain rheumatic diseases." (PMID 33673730, 2021). "Leptin has been described as a key factor in the pathophysiology of rheumatic diseases due to its capability to modulate bone and cartilage metabolism and to influence innate and adaptive immune responses." (PMID 29910742, 2018). "Among the different adipokines, leptin and adiponectin were identified as relevant factors involved in interactions between metabolism and rheumatic disorders." (PMID 24741591, 2014). "There are several contradictory reports on leptin in rheumatic diseases." (PMID 23115723, 2012). "Leptin is a peptide hormone with a role in bone metabolism and rheumatic diseases." (PMID 20141628, 2010). "The data presented here suggest that leptin could be considered a link between immunometabolism and rheumatic diseases and regulation or modulation of its signalling pathways may represent innovative therapeutic strategies for autoimmune and rheumatic disorders." (PMID 33673730, 2021).
acute lymphoblastic leukemia (10 papers, 2010 to 2025). Leukemia with an acute onset, characterized by the presence of lymphoblasts in the bone marrow and the peripheral blood. "They reasoned that hypothalamic leptin resistance should be considered in obese patients with acute lymphocytic leukemia (ALL)." (PMID 37626742, 2023). "Acute lymphoblastic leukemia (ALL) pediatric patients exhibit high levels of leptin and low levels of APN at the diagnosis, while the balance of the adipokines progressively return to homeostatic values during therapy, representing a sign of good health." (PMID 32354024, 2020).
acute respiratory distress syndrome (10 papers, 2016 to 2025). Progressive and life-threatening pulmonary distress in the absence of an underlying pulmonary condition, usually following major trauma or surgery. "Elevated levels of leptin in the bloodstream can cause an immune-impairing state best described as “leptin resistance”, and elevated levels of leptin in obese patients can cause aggravated cases of acute respiratory distress syndrome." (PMID 35711466, 2022). "Adipose tissue is a proinflammatory tissue with an increased expression of cytokines, particularly adipokines like leptin, which associate with an increased inflammatory response, reduced ciliary clearance, and acute respiratory distress syndrome." (PMID 33844896, 2021). "Furthermore, leptin levels in bronchoalveolar lavage fluid reportedly increased in patients with acute respiratory distress syndrome (ARDS), and higher leptin levels were associated with higher mortality in nonobese patients." (PMID 31324858, 2019). "Leptin, an adipocyte‐derived cytokine‐like hormone, plays a crucial role in metabolism and immunity but its role in acute lung disorders such as acute respiratory distress syndrome (ARDS) remains controversial." (PMID 40635334, 2025). "In lung physiology, leptin contributes to maturation and alveolar development, but its role in acute lung disorders such as acute respiratory distress syndrome (ARDS) remains controversial." (PMID 40635334, 2025). "Among patients with ALI or acute respiratory distress syndrome (ARDS), levels of leptin in bronchoalveolar lavage (BAL) fluid correlate with TGF-β1." (PMID 27642238, 2016).